SND1 (staphylococcal nuclease and tudor domain containing 1)
Diseases named in the same sentence as SND1 in open-access papers (continued):
Sharing a sentence is not in itself a finding about the gene and the disease.
colorectal adenoma (1 paper, 2023). An adenoma that arises from the colon or rectum. "Our results showed that all the genes of ZNF471, SND1, SPOCK1, FBLIM1, and OTX1 methylation with the area under receiver operating curve (ROC) more than 0.90 were significantly high in the colorectal adenoma and CRC compared with the normal group." (PMID 37779184, 2023). "Based on the results of the methylation chip of Illumina Infinium 450K detection and bioinformatic analysis, five hypermethylated genes, ZNF471, SND1, SPOCK1, FBLIM1, and OTX1, were selected for further investigation in the colorectal adenoma, CRC, and control normal tissues in our study." (PMID 37779184, 2023).
COVID-19 (1 paper, 2023). A disease caused by infection with severe acute respiratory syndrome coronavirus 2. "Finally, a genome-wide association study (GWAS) reported rare sequence variants in introns of SND1 that are associated with severe COVID-19 and increased hospitalization with nominal significance, albeit not at genome-wide significance levels." (PMID 37794589, 2023).
esophageal squamous cell carcinoma (1 paper, 2024). Esophageal squamous cell carcinoma (ESCC) is a type of esophageal carcinoma (EC) that can affect any part of the esophagus, but is usually located in the upper or middle third. "Moreover, KDM6A H101D & P110S, N1156T and D1216N mutations identified in esophageal squamous cell carcinoma (ESCC) patients showed the increased interaction with SND1 and enhanced resistance to genotoxin." (PMID 38850159, 2024).
Insulin resistance (1 paper, 2021). Increased resistance towards insulin, that is, diminished effectiveness of insulin in reducing blood glucose levels. "Although we have previously implicated gain of function of SND1 in improving insulin resistance in the global SND1 transgenic mice in an HFD-induced mouse model, the loss of function of SND1 in the liver in regulating pathophysiologic function is unclear." (PMID 34608846, 2021). "Then, we performed a series of experiments, such as fasting/refeeding assay, glucose/insulin tolerance test, and acute insulin response assay, to analyze the in vivo role of hepatic SND1 in the HFD-induced insulin resistance." (PMID 34608846, 2021). "Previously, we observed a reduced accumulation of triglyceride and the improved fatty liver and insulin resistance in the liver tissue of global SND1 transgenic mice under the treatment of a high-fat diet." (PMID 34608846, 2021). "To study the impact of hepatocyte-specific SND1 deletion on liver insulin resistance and ALF, we first successfully constructed the liver LKO mice of SND1." (PMID 34608846, 2021). "Thus, we are interested in investigating the potential role of hepatic SND1 expression in the liver insulin resistance of mice." (PMID 34608846, 2021). "We then investigated whether hepatocyte-specific deletion of SND1 in mice affects HFD-induced liver insulin resistance and LPS/D-GalN-induced ALF." (PMID 34608846, 2021). "Although the hepatocyte-specific deletion of SND1 does not remarkably influence liver insulin resistance, it is clearly warranted to analyze further the potential effects of SND1 in adipose or muscle tissues." (PMID 34608846, 2021).
osteosarcoma (1 paper, 2021). A usually aggressive malignant bone-forming mesenchymal neoplasm, predominantly affecting adolescents and young adults. "The serum PGE2 level had a significant positive association with the SND1 mRNA expression level in osteosarcoma tissues." (PMID 34199169, 2021). "Zhou and coworkers revealed that osteosarcoma tissues from different patients expressed significantly high SND1 mRNA and protein expression compared to normal bone tissues." (PMID 34199169, 2021). "On the other hand, overexpression of staphylococcal nuclease domain containing 1 (SND1) has been found in several malignancies including osteosarcoma, which is the most frequent primary bone tumor." (PMID 34199169, 2021). "Targeting of SND1 as a new antitumor strategy for patients with osteosarcoma and SND1 may also act as a potential biomarker of the therapeutic strategies utilizing COX2 inhibitors." (PMID 34199169, 2021).
ovarian tumor (1 paper, 2025). "Similarly to MTDH, analysis of cProSite data indicated significantly higher levels of SND1 expression in ovarian tumor tissues relative to adjacent normal tissues (p-value < 0.0001)." (PMID 41286067, 2025).
papillary thyroid carcinoma (1 paper, 2021). "Three cases were characterized by NCOA4-RET, CCDC6-RET, and SND1-BRAF fusions, which are more commonly seen in papillary thyroid carcinoma." (PMID 33441414, 2021).
primary effusion lymphoma (1 paper, 2025). A large B-cell lymphoma located in the body cavities, characterized by pleural, peritoneal, and pericardial fluid lymphomatous effusions and that is always associated with human herpes virus-8 (HHV-8). "In primary effusion lymphoma (BCBL-1) cells, others noted that YTHDFs protein members had a positive role in the viral lytic cycle; more interestingly, authors identified the staphylococcal nuclease domain-containing protein 1 (SND1), as a novel m6A-reader in the KSHV lytic cycle." (PMID 41019992, 2025).
prostate tumor (1 paper, 2023). "Ablation of Snd1 had a prominent negative impact on prostate tumor development and growth." (PMID 37973913, 2023).
rectal cancer (1 paper, 2022). A primary or metastatic malignant neoplasm that affects the rectum. "Non targeted novel fusions were also identified including FGFR1-NRG1 in breast, BRAF-MRPS33 in prostate, SND1-MET in lung, PCM1-BRAF in sarcoma and TMEM178B-MET in rectal cancer." (PMID 35984852, 2022).
serous adenocarcinoma (1 paper, 2016). An adenocarcinoma that is characterized by the presence of papillary patterns and cellular budding. "When analysis was restricted to the 6,500 patients with invasive serous adenocarcinomas, the magnitude of association was slightly attenuated for ADAR3 rs77027562 (OR = 1.33, P = 6.1×10−3) and slightly stronger for SND1 rs185455523 (OR = 0.60, P = 1×10−4)." (PMID 27911851, 2016).
cancer (67 papers, 2015 to 2025). A tumor composed of atypical neoplastic, often pleomorphic cells that invade other tissues. "To date, the oncogenic role of SND1 in various cancers is relatively well established; however, the underlying mechanism remains primarily focused on transcriptional regulation." (PMID 40775338, 2025). "SND1 is highly expressed in most cancer cells, and its expression level is associated with prognosis of patients." (PMID 38358895, 2024). "Upregulation or/and function activation of SND1 was considered to positively associated with cancer progression." (PMID 36213325, 2022). "Both PRMT5 and SND1 are broadly expressed and their deregulation is reported to be associated with a range of disease phenotypes, including cancer." (PMID 33768972, 2021). "Clinical and experimental studies show a close association between overexpression of SND1 and progression and aggressiveness of a spectrum of common cancers that include colon, breast, prostate, lung, glioma, melanoma, and liver cancer." (PMID 30619748, 2018). "SND1 is indispensable for normal development and stress resistance, whereas its deregulation is closely associated with various types of cancer." (PMID 30344928, 2018). "Upregulation of Staphylococcal nuclease and tudor domain containing 1 (SND1) is linked to cancer progression and metastatic spread." (PMID 29296233, 2017). "Although extensive research has been conducted on the expression patterns and biological functions of SND1 in various cancers, the underlying mechanisms driving overexpression remain unclear." (PMID 40775338, 2025). "Thus, targeting KDM6A mutations that specifically interacting with SND1 in ESCC can be exploited as cancer cell-specific therapeutic strategies for chemotherapy." (PMID 38850159, 2024). "Snd1 has also been associated with the malignant behavior of diverse types of cancer." (PMID 37771775, 2023). "Thus, accumulative data indicate the role of SND1 as a diagnostic but also a prognostic cancer biomarker." (PMID 34809722, 2021). "While the role that PRMT5 plays in the development of HCC is largely circumstantial—elevated PRMT5 levels clearly correlate with the promotion of HCC and poor prognosis of these cancer patients—its effector molecule, SND1, is more solidly implicated as a driver of HCC." (PMID 33768972, 2021). "Tudor-SN is a member of the RISC complex and also known as SND1, and it has been implicated in various cancers and has been shown to regulate miRNA processing and expression by degrading primary-miRNA transcripts that undergo adenosine deaminase acting on RNA (ADAR) editing." (PMID 26097876, 2015). "Further functional analyses of MTDH and the interacting protein SND1 with RNA silencing, as well as targeting their interaction, revealed that disrupting this interaction leads to the dysregulation of several pathways associated with cancer progression and invasion." (PMID 41286067, 2025). "Collectively, these findings emphasize the shared role of MTDH and SND1 in promoting cancer progression and highlight their potential as therapeutic targets." (PMID 41286067, 2025). "As an evolutionarily conserved protein, SND1 has emerged not only as a biomarker, but also as a promoter of cancer progression." (PMID 39895626, 2025). "Taken together, the oncogenic potential of SND1 in cancer cells renders it to become a key player in mediating cell death." (PMID 39885142, 2025). "SND1 is an emerging drug target in cancer, and targeting protein–protein interaction sites in SND1, such as the interaction between SND1 and metadherin (MTDH), is an active area of research." (PMID 39169000, 2024). "This work represents the novel characterization of how lncTCF7 and SND1 interact to regulate the SWI/SNF chromatin remodeling complex, which is frequently mutated or dysregulated in cancers and neurodevelopmental disorders." (PMID 39169000, 2024).
cancer (continued). "Although it has been reported that SP1 and NFYA are transcription factors that regulate the transcription activity of Snd1 in cancer cells, in this study, we demonstrated that both of them did not affect Snd1 transcription activity in VSMCs." (PMID 38279051, 2024). "Some studies suggested that SND1 plays important roles in cancer by interacting with other transcription factors, including PPARγ, signal transducer and activator of transcription 5/6 (STAT6/5) and myeloblastosis oncogene (c-Myb)." (PMID 39436790, 2024). "SND1 and its binding partner MTDH are two proteins that are prominently implicated in cellular transformation, cancer metastasis, and drug resistance." (PMID 37973913, 2023). "While the important role of SND1/MTDH in cancer is well documented, the molecular mechanisms of their function are only beginning to be understood." (PMID 37973913, 2023). "For example, the carcinogenic effects of SND1 in human tumors were identified in a pan-cancer analysis, which showed that SND1 was found to promote cell proliferation and tumor progression through inducing mitochondrial autophagy." (PMID 37893001, 2023). "In our PB-Cre4/Ptenfl/fl/ERG/Snd1fl/fl model of PC the cancer-driving Pten inactivation co-occurs with deletion of Snd1, as both of these events are carried out by same Cre recombinase." (PMID 37973913, 2023). "SND1/MTDH are frequently overexpressed and associated with poor prognosis across many cancer types including PC22–26." (PMID 37973913, 2023). "Staphylococcal nuclease domain-containing 1 (SND1) is evolutionarily conserved and highly expressed in various cancers." (PMID 37885030, 2023). "In the light of evidence that Snd1 is overexpressed in several cancer types, it is highly relevant to investigate the effect and mechanisms of Snd1 and its overexpression on hypoxia response and cancer." (PMID 37151849, 2023). "The functional role of SND1 in cancer cells remains elusive, and the SND1-regulated pathways are presently unidentified." (PMID 35804872, 2022). "SND1 has been proposed to enhance stress tolerance in cancer cells, but the molecular mechanisms are still poorly understood." (PMID 35804872, 2022). "Taken together, we demonstrate as proof-of-concept a mechanism and an inhibitor compound for SND1 regulation of the survival of cancer cells through tumor suppressor miRNAs." (PMID 35804872, 2022). "We demonstrated that inhibition of the RNA-binding ability of SND1 leads to increased sensitivity of cancer cells to Bcl-2 family inhibitor navitoclax." (PMID 35804872, 2022). "Truncations of Tmod3 induced by AEP contribute to cancer progression by facilitating actin remodeling and nuclear SND1 mediated RhoA/CDKs transcription." (PMID 35765111, 2022). "Taken together, we have here demonstrated that silencing of SND1 increases the level of several tumor suppressor miRNAs and sensitizes cancer cells especially to MEK-ERK pathway inhibitors and Bcl-2/Bcl-XL inhibitor navitoclax." (PMID 35804872, 2022). "These two truncations played completely different roles in promoting cancer than those exhibited by Tmod3 through actin remodeling and SND1/RhoA-mediated cell proliferation." (PMID 35765111, 2022). "SND1 is overexpressed in several cancers, including colorectal, breast, prostate, and hepatocellular cancers, and gliomas." (PMID 35804872, 2022). "Clinical and experimental studies have indicated that SND1 is closely correlated with the progression and invasiveness of common cancers as a potential oncogene, but this gene has rarely been studied in fungi." (PMID 34378960, 2021). "In previous studies of oncogenes, SND1 was found to be highly expressed during the stage of malignant proliferation and aggressiveness of many common human cancer cells." (PMID 34378960, 2021). "But on the contrary to the previous investigations, our study revealed the contribution of SND1 to the transcriptional regulation of key genes involved in cancer development, focusing on hTERT." (PMID 33305480, 2021).
cancer (continued). "The oncogene role of MAEL and SND1 have been shown to enhance the development and maintain the stemness of carcinoma." (PMID 35083142, 2021). "Consistent with the involvement of SND1 in cancer metastasis via ERK signaling and EMT revealed in previous studies, we found that p-ERK1/2 and the EMT inducer snail were significantly reduced in 786-O-shSND1 cells using western blotting." (PMID 31978894, 2020). "More recently, a negative correlation of Staphylococcal nuclease and tudor domain containing 1 (SND1) with MGL has been found in cancer cells, implying that SND1 and MGL influence each other’s expression." (PMID 32290093, 2020). "Extensive research also supports the conclusion that SND1 is an oncoprotein in a variety of cancers involving multiple processes and that it also acts as an essential effector in promoting EMT in cancer." (PMID 33519900, 2020). "In recent years, SND1 has emerged as one of the most important modulators of the molecular network in cancer cells and a molecular target for cancer treatment." (PMID 31240215, 2019). "More than two decades of research has accumulated evidence of the role of SND1 as an oncogene in various cancers." (PMID 32258418, 2018). "Several works have shown that knocking down endogenous SND1 inhibits proliferation in diverse cancer cell lines." (PMID 30619748, 2018). "Recently, SND1 has gained attention as a potential disease biomarker due to its positive correlation with cancer progression and metastatic spread." (PMID 30619748, 2018). "All these results further strengthen the role of SND1 as a transcriptional modulator essential for normal cell growth, differentiation and proliferation of cancer cells, and response to various types of cellular and environmental stresses." (PMID 26323317, 2015). "Although SND1 is known to stimulate tumor growth in multiple cancer contexts including CRCs, its upstream signal in CRCs has previously not been investigated." (PMID 25965817, 2015). "The present review provides a comprehensive description of the functional aspects of SND1 that are relevant to cancer development and progression." (PMID 25405367, 2015). "Despite this, the role of SND1 in cancer development and the molecular mechanisms underpinning SND1 gene promoter activation are far from being elucidated." (PMID 26323317, 2015). "Here, we describe the crucial role of SND1 in cancer development and progression, and highlight SND1 as a potential target for therapeutic intervention." (PMID 25405367, 2015). "We found that SND1 could interact with more than 50 proteins responsible for driving various types of cancers." (PMID 40841409, 2025). "Additionally, SND1 is frequently overexpressed in multiple types of cancer, such as colon, prostate, breast, bladder and hepatocellular carcinomas and exhibits cytoprotective and oncogenic activity by promoting the proliferation of tumor cells." (PMID 39885142, 2025). "Furthermore, among all the gene partners of BRAF, staphylococcal nuclease and Tudor domain containing 1 (SND1), an oncogene in several types of cancer acts in addition to posttranscriptional modifications." (PMID 38779099, 2024). "SND1 participates in tumorigenesis, tumour invasion and metastasis in different cancers." (PMID 37885030, 2023). "In different cancer types, SND1 promotes a malignant phenotype through different mechanisms." (PMID 37885030, 2023). "Additionally, SND1 has garnered attention as a metastatic cancer biomarker given its positive correlation with cancer progression." (PMID 37838950, 2023). "In this study, we propose a novel mechanism for how SND1 affects the survival of cancer cells." (PMID 35804872, 2022). "Furthermore, SND1 knockdown showed synergetic effects with cancer drugs through MEK-ERK and Bcl-2 family-related apoptotic pathways." (PMID 35804872, 2022). "SND1 is an RNA-binding protein overexpressed in large variety of cancers." (PMID 35804872, 2022).